DES (desmin)
Diseases named in the same sentence as DES in open-access papers (continued):
Sharing a sentence is not in itself a finding about the gene and the disease.
Desmin-Related Myopathy (2 papers, 2013 to 2025). "The human disease produced by the CryABR120G allele is sometimes called Desmin-Related Myopathy (DRM), owing to the presence of desmin in the characteristic cytoplasmic protein aggregates, and to similarities with diseases caused by mutations in the gene encoding the intermediate filament desmin." (PMID 23818860, 2013).
diabetic kidney disease (2 papers, 2016 to 2024). Progressive kidney disorder caused by vascular damage to the glomerular capillaries, in patients with diabetes mellitus. "Increased expression of desmin and vimentin, both observed in the present study, is associated with damage to podocytes in diabetic nephropathy and several other renal disease models." (PMID 26881253, 2016).
Duchenne muscular dystrophy (2 papers, 2018 to 2024). Duchenne muscular dystrophy (DMD) is a neuromuscular disease characterized by rapidly progressive muscle weakness and wasting due to degeneration of skeletal, smooth and cardiac muscle. "In the murine model of the Duchenne muscular dystrophy (the dystrophin/utrophin-deficient mouse) large clusters of nestin+ striated cells co-expressing cardiac troponin I, desmin and connexin 43, were present in the hearts near the end stage of the disease." (PMID 36690826, 2024). "The muscles of patients with Duchenne muscular dystrophy (DMD) exhibit a high regeneration rate and increased DUX4c levels, with strong DUX4c immunolabeling being observed in some desmin-positive regenerating fibers." (PMID 29329560, 2018).
embryonal sarcoma (2 papers, 1987 to 2022). "UESLs are usually diffusely positive for vimentin and a1-antitrypsin and focally positive for cytokeratin, desmin, α-SMA, muscle-specific actin, CD68, myoglobin, neuron-specific enolase, S100, and CD34, suggesting that an embryonal sarcoma is undifferentiated." (PMID 36107353, 2022).
Emery-Dreifuss muscular dystrophy (2 papers, 2022 to 2024). Emery-Dreifuss muscular dystrophy (EDMD) is characterized by muscular weakness and atrophy, with early joint contractures and cardiomyopathy. "Interestingly, in Emery-Dreifuss Muscular Dystrophy (EDMD2) myoblasts exposed to mechanical stretching, the recruitment of desmin and plectin to the nucleus and nuclear orientation were impaired, suggesting that a functional lamin A/C is crucial for the response to mechanical strain." (PMID 38247853, 2024).
epilepsy (2 papers, 2016 to 2025). A brain disorder characterized by episodes of abnormally increased neuronal discharge resulting in transient episodes of sensory or motor neurological dysfunction, or psychic dysfunction. "The killing of the muscles cells by the epilepsy patients’ IgG is clearly seen when comparing the representative confocal microscopy images of the Sytox Green+ dead cells aside the muscle-specific desmin+ cells in the: A." (PMID 41458379, 2025).
epithelial mesotheliomas (2 papers, 2017). "In particular the authors evidenced an altered expression of nuclear lamin and related filament proteins such as Vimentin and Desmin suggesting their ability to distinguish epithelioid mesothelioma from other lung malignancies with good values of sensibility and specificity." (PMID 28348450, 2017).
familial cardiomyopathies (2 papers, 2017). "Three different guide RNAs for human gene Desmin and four for human gene LAMP2, which are mutated genes in the hereditary cardiomyopathy, were designed with web-based software ZiFiT Targeter." (PMID 29212218, 2017).
Follicular carcinoma (2 papers, 2018 to 2025). "In follicular thyroid carcinomas, the rhabdoid inclusions are vimentin-positive but lack immunoreactivity for cytokeratins, thyroglobulin, smooth-muscle actin, and desmin." (PMID 29938394, 2018).
glomerulonephritis (2 papers, 2014 to 2023). A renal disorder characterized by damage in the glomeruli. "Notably, the cortical mRNA expression of desmin, which is a podocyte activation and damage marker, was not affected by LPS-induced glomerulonephritis." (PMID 37475889, 2023).
granulosa cell tumor (2 papers, 2016 to 2022). A slow-growing, malignant tumor, characterize by the presence of granulosa-like cells and Call-Exner bodies, that is almost always found in the ovary. "Luteinized granulosa cell tumor shows varying presence of nuclear grooves with vimentin, inhibin, calretinin, CD99, and SMA positivity with variable immunoreactivity for desmin and PanCK and negativity with EMA." (PMID 27818820, 2016).
inclusion body myositis (2 papers, 2019 to 2025). A slowly progressive degenerative inflammatory disorder of skeletal muscles characterized by late onset weakness of specific muscles and distinctive histopathological features. "Desmin inclusions are present in pathologic myofibers from patients with MFM, and are a principal component of protein inclusions in other protein aggregate myopathies not due to desmin mutations including acquired myopathies, such as sporadic inclusion body myositis." (PMID 31371504, 2019).
intrauterine growth restriction (2 papers, 2019 to 2021). "Increased relative protein level of cytoskeletal β-actin and desmin can be found in pig jejunum caused by intrauterine growth restriction." (PMID 30941268, 2019). "While results of desmin and troponin T degradation did not support increased toughness of IUHS loin muscles would owe to differential proteolysis, there is some evidence to suggest intrauterine growth restriction can increase shear force through upregulation of calpastatin." (PMID 33800814, 2021).
ischemic cardiomyopathy (2 papers, 2022 to 2025). Ischemic cardiomyopathy is a cardiomyopathy in which a weakness in the muscle of the heart due to inadequate oxygen delivery to the myocardium with coronary artery disease being the most common cause. "In this study, we showed that the expression of high MW Ldb3 isoforms decreased in LV of HF patients with ischemic cardiomyopathy, as well as in LV of HF rats in which we have previously observed LV structural alterations, desmin aggregate accumulation, and sarcomere disruption." (PMID 35806378, 2022).
kidney damage (2 papers, 2016 to 2024). "In our study, ADR-induced nephropathy manifested as extensive podocyte foot process effacement under electron microscopy, along with decreased expression of nephrin and increased expression of desmin." (PMID 39408958, 2024). "In order to identify phosphoproteins that may play a role in salt-induced kidney damage, we examined changes in phosphorylation levels of lamin A and phospholamban as well as their downstream genes desmin and SERCA2a, which altered significantly in response to high salt intake in 5/6Nx rats." (PMID 27775022, 2016).
lipoblastoma (2 papers, 2021 to 2025). A lipoma usually occurring in the extremities of young children (usually boys). "Lipoblastomas typically occur in infants and children, and even in older children and adult patients, positivity for PLAG1, CD34, and desmin, along with PLAG1 and HMGA2 rearrangements, aids in diagnosis." (PMID 41230282, 2025). "Lipoblastoma typically occurs in infants and children and often shows pleomorphic adenoma gene 1 (PLAG1) overexpression and PLAG1/HMGA2 rearrangements, with frequent cluster of differentiation 34 (CD34) and desmin expression." (PMID 41230282, 2025). "Additionally, desmin immunohistochemistry revealed that the tumor involved lingual muscle fibers, which may indicate the infiltrative nature of lipoblastoma rather than SCLs or LLTs." (PMID 41230282, 2025). "Additionally, negative results for DDIT3, CD34, desmin, and PLAG1 support the diagnosis and help exclude myxoid liposarcoma and “adult” lipoblastoma." (PMID 41230282, 2025).
lung adenocarcinoma (2 papers, 2020). A carcinoma that arises from the lung and is characterized by the presence of malignant glandular epithelial cells. "Lung adenocarcinoma was positive for MCK and TTF-1, and MGs showed immunoreaction for Vimentin, Desmin and SMA; Ki67 expression of classical OPA was higher than atypical OPA and MGs." (PMID 32807166, 2020).
lymph node metastasis (2 papers, 2017 to 2023). "All the cases had no lymph node metastasis and were negative for desmin." (PMID 28915565, 2017).
metastatic carcinoma (2 papers, 2013 to 2025). A carcinoma which has spread from the original site of growth to another anatomic site. "Moreover, the positive expression of Desmin and MyoD1, negative expression of CK can also rule out the possibility of metastatic carcinoma." (PMID 23379991, 2013).
Myocardial fibrosis (2 papers, 2010 to 2025). "CMR is superior to conventional echocardiography for the detection of myocardial fibrosis in desmin-related cardiomyopathy, which may be useful to detect early cardiac involvement and predict the patient prognosis." (PMID 21083940, 2010).
myositis (2 papers, 2013 to 2023). "On the other hand, we noted that other muscle fibers in myositis areas and adjacent areas showed a very marked desmin immunoreaction." (PMID 24049666, 2013). "Other muscle fibers in the myositis areas and in normally appearing muscle tissue of experimental animals and all muscle fibers in the specimens of control animals showed the characteristic desmin immunoreaction pattern, that is, a striated reaction pattern in longitudinally cut muscle fibers." (PMID 24049666, 2013).
myxoma (2 papers, 2016 to 2024). A benign soft tissue neoplasm characterized by the presence of spindle and stellate cells, lobulated growth pattern, and myxoid stroma formation. "Myxoma is often immunohistochemically CD34-positive, rarely SMA-positive, and desmin- and S100-negative." (PMID 39410565, 2024).
nemaline myopathy (2 papers, 2022 to 2023). Nemaline myopathy (NM) encompasses a large spectrum of myopathies characterized by hypotonia, weakness and depressed or absent deep tendon reflexes, with pathologic evidence of nemaline bodies (rods) on muscle biopsy. "Proteolysis in skeletal muscle is closely regulated by E3 ubiquitin ligases such as TRIM32, that was shown to target actin and desmin, and mutations in TRIM32 result in LGMD, nemaline myopathy or MFM." (PMID 37174721, 2023).
nephrotic syndrome (2 papers, 2015 to 2025). A collection of symptoms that include severe edema, proteinuria, and hypoalbuminemia; it is indicative of renal dysfunction. "SFN has a protective effect on MN, as reflected by alleviation of nephrotic syndrome, amelioration of podocyte foot process fusion, increased expression and normalization of podocin, and decreased expression of desmin in the glomeruli." (PMID 39850113, 2025). "To further confirm glomerular Angptl4 expression in MCD, we stained for Angptl4, desmin and synaptopodin in samples obtained from nephrotic syndrome patients with MCD (n = 15), MN (n = 5), FSGS (n = 5) and mesangial proliferative glomerulonephritis (MsPGN, n = 5)." (PMID 26352670, 2015).
non-alcoholic steatohepatitis (2 papers, 2020 to 2023). "Nevertheless, no alteration in the expression of pannexin 1 (Panx1, recently related to inflammation in non-alcoholic steatohepatitis and to liver damage) or the fibrosis markers transforming growth factor β1 (Tgfb1) or desmin (Des) was observed." (PMID 33374541, 2020). "Vgll3 expression was also increased in the fibrotic liver of non-alcoholic steatohepatitis (NASH) model mice, specifically in hepatic stellate cells expressing Desmin." (PMID 36754961, 2023).
ovarian neoplasm (2 papers, 2023 to 2024). A benign, borderline, or malignant neoplasm involving the ovary. "After removal, a thorough analysis using immunohistochemical markers such as desmin, inhibin, and SMA is crucial for accurately classifying and differentiating ovarian fibromas from other ovarian neoplasms." (PMID 39553140, 2024).
seminoma (2 papers, 2022 to 2025). A radiosensitive malignant germ cell tumor found in the testis (especially undescended), and extragonadal sites (anterior mediastinum and pineal gland). "In TGCC samples, desmin was expressed in Sertoli cells from GCNIS-containing tubules and in Sertoli cells from tubules with active spermatogenesis from patients with either seminoma or non-seminoma." (PMID 36428571, 2022).
skeletal muscle tumor (2 papers, 2017 to 2025). "AE1/AE3 serves as an epithelial tumor marker, Vimentin identifies fibroblasts, CD68 highlights monocytes, histiocytes, osteoclasts, mast cells, and giant cells, and Desmin is specific for skeletal muscle tumors." (PMID 41333207, 2025). "Since it is a skeletal muscle tumor, it is immunopositive for HHF35, myoglobin and desmin." (PMID 27918739, 2017).
Sleep apnea (2 papers, 2019 to 2024). An intermittent cessation of airflow at the mouth and nose during sleep is known as sleep apnea. "Cytoskeletal proteins desmin and dystrophin were morphologically evaluated in the uvula muscle of 22 patients undergoing soft palate surgery due to snoring and sleep apnea and in 10 healthy controls." (PMID 30764835, 2019). "The high proportion of fibres with disorganized desmin as well as histopathological changes such as atrophic and hypertrophic fibres, fascicular atrophy and fibrosis in the palate muscles of snorer and sleep apnea reflect muscle weakness in the upper airways due to local injury." (PMID 30764835, 2019). "Therefore, we aimed to investigate for desmin and dystrophin abnormalities in soft palate muscles of snoring and sleep apnea patients and to evaluate whether these abnormalities relate to deviations in swallowing function and severity of obstructive sleep apnea." (PMID 30764835, 2019). "Although the proportion of desmin and dystrophin abnormalities in sleep apnea patients were significantly higher than in controls, no relation to the severity of sleep apnea (AHI) could be established." (PMID 30764835, 2019).
soft tissue tumors (2 papers, 2014 to 2023). "Even the negativity of the expression of some genes such as EMA, H-caldesmon, desmin, CD31, S100 is used for diagnosis, especially to differentiate SFTP from other soft tissue tumours." (PMID 36769614, 2023).
thymoma (2 papers, 2016 to 2020). A neoplasm arising from the epithelial cells of the thymus. "Recently, WHO had suggested a dozen of histochemical markers to differentiate type A and type B thymoma, including TdT, CD1a, CD99, PSMB11 (Beta5T), PRSS16, Cathepsin V, and desmin." (PMID 31967407, 2020).
Type 1 diabetes (2 papers, 2022 to 2023). "Type 1 diabetes induced a significant upregulation in the mean fold change of relative mRNA expression of the renal cytoskeleton (stress indicators): desmin, vimentin, nestin, fibronectin-1, Coli-1, and α-SMA." (PMID 38044936, 2023).
uterine sarcoma (2 papers, 2023 to 2024). "IHC markers could be critical clues for diagnosis; usually, TRK, S100, and CD34 were stained positive, with markers of smooth muscle (desmin and caldesmon) and hormone receptors (ER and PR) stained negative for NTRK fusion uterine sarcoma." (PMID 36994196, 2023).
Achalasia (1 paper, 2024). A disorder of esophageal motility characterized by the inability of the lower esophageal sphincter to relax during swallowing and by inadequate or lacking peristalsis in the lower half of the body of the esophagus. "Additionally, biopsy and immunohistochemistry for markers like desmin and myogenin, which are specific to RMS, are crucial in differentiating ERMS from benign esophageal strictures or achalasia." (PMID 39703342, 2024).
acyl-CoA dehydrogenase deficiency (1 paper, 2022). "However, this patient showed an acyl CoA dehydrogenase deficiency-characteristic increase in the C8/C10-carnitine ratio with a value of 0.98 (normal range, 0.60 to 0.00), a finding that was also present in our desmin knock-out mice (2.12 vs. 1.85, p = 0.049)." (PMID 36233322, 2022).
adenofibroma (1 paper, 2023). A benign neoplasm characterized by the presence of connective tissue stroma and epithelial structures. "The spindle component is usually negative for both actin and desmin in adenofibroma." (PMID 36644654, 2023).
adenosarcoma (1 paper, 2020). A low grade malignant neoplasm characterized by the presence of a benign epithelial component (tubular and cleft-like glands) and a low grade sarcomatous component that contains varying amounts of fibrous and smooth muscle tissues. "Other markers for adenosarcomas are SMA (50–68%), desmin (32–62.5%), CD34 (35%), and cytokeratin (25–27%)." (PMID 32972432, 2020).
Alexander disease (1 paper, 2020). Alexander disease (AxD) is a rare neurodegenerative disorder of the astrocytes comprised of two clinical forms: AxD Type I and Type II manifesting with various degrees of macrocephaly, spasticity, ataxia and seizures and leading to psychomotor regression and death. "In some neurodegenerative diseases such as Alexander’s disease and Alzheimer’s disease, keratin and desmin aggregates and inclusions can be observed, and dysregulated keratin expression was observed in Alzheimer’s disease." (PMID 32899810, 2020).
anaplastic thyroid carcinoma (1 paper, 2024). "Notably, rhabdomyosarcomatous differentiation of anaplastic thyroid carcinoma is characterized by weak staining for epithelial markers and strong staining for vimentin, actin, desmin, and myoglobin." (PMID 39420880, 2024).
Arthritis (1 paper, 2017). Inflammation of a joint. "In the present study, we further investigated the underling mechanisms of arthritis-induced muscle dysfunction and found that desmin as well as actin are aggregated in AIA EDL muscles." (PMID 28636643, 2017).
autoimmune disease (1 paper, 2012). A disorder resulting from loss of function or tissue destruction of an organ or multiple organs, arising from humoral or cellular immune responses of the individual to their own tissue constituents. "Interestingly, Desmin has been identified as an autoantigen in other autoimmune diseases and is therefore not uniquely associated with IBM." (PMID 23071619, 2012).
biliary tract cancer (1 paper, 2020). "However, patients with ampulla of Vater (3-year survival rate, 34% vs 86%; P = 0.192) and biliary tract cancers (3-year survival rate, 100% vs 25%; P = 0.250) with VI showed a tendency of shorter disease-free survival by dual CD31‒desmin immunolabeling." (PMID 33253282, 2020).
bladder leiomyoma (1 paper, 2024). A well-circumscribed benign smooth muscle neoplasm arising from the bladder. "Immunohistochemically, the majority of bladder leiomyomas show significant and wide immunoreactivity for smooth muscle actin, muscle-specific actin, desmin, and vimentin, whereas typically absent reactivity of antibodies for cytokeratin and S100 protein." (PMID 38983791, 2024).
breast leiomyosarcoma (1 paper, 2025). An aggressive malignant smooth muscle neoplasm, arising from the breast. "Histopathological analysis confirmed metastatic breast leiomyosarcoma, supported by characteristic immunohistochemical profile: positive for smooth muscle actin (SMA), cluster of differentiation (CD) 34, and CD10, negative for Desmin and CD117, and with a low proliferative index (Ki-67 5-10%)." (PMID 41244917, 2025).
Cachexia (1 paper, 2018). Severe weight loss, wasting of muscle, loss of appetite, and general debility related to a chronic disease. "Disintegration of the sarcomere during cachexia may be further compounded by desmin dysregulation, and thereby loss of connectivity to mitochondria." (PMID 29774118, 2018).